RHOA (ras homolog family member A)
Diseases named in the same sentence as RHOA in open-access papers (continued):
Sharing a sentence is not in itself a finding about the gene and the disease.
breast carcinoma (continued). "Using active MMP-9 activity levels in serum and RhoA expression patterns in circulating leucocytes, the authors developed a non-invasive multiparametric approach to stratify patients with breast cancer." (PMID 30262739, 2018). "Our findings are consistent with other studies that showed Sema3A treatment of breast carcinoma cells increases RhoA activity to inhibit cell migration." (PMID 28182100, 2017). "MiR-155 has been reported to be overexpressed in colon cancer and previous studies have shown that RhoA is a direct target of miR-155 in different cell types, including breast cancer, endothelial, and epithelial cells." (PMID 28146427, 2017). "Hypoxia-triggered activation of RhoA signaling was shown to induce focal adhesions and motility in breast cancer cells." (PMID 28831110, 2017). "Here, we aim to compare the function of RhoC and its homolog family member RhoA in breast cancer progression." (PMID 29152087, 2017). "We confirmed that simvastatin caused the translocation of the small Rho GTPases RhoA, Cdc42, and Rac1/2/3 from cell membranes to the cytosol in U251 (glioblastoma), A549 (lung adenocarcinoma) and MDA-MB-231(breast cancer)." (PMID 28344327, 2017). "To obtain more insight into the role of RhoA and RhoC in the development of human breast cancer, we established stable cell lines whose expression of RhoA or RhoC can be induced reversibly." (PMID 29152087, 2017). "Taken together, these results suggested that NRF2 positively regulates the expression of RhoA in human breast cancer cells." (PMID 27713154, 2016). "Several studies have shown that elevated expression of RhoA and ROCK1 in breast cancer tissues is associated with poor prognosis." (PMID 27203208, 2016). "It has been recently shown that the SASP from senescent stromal fibroblasts inhibits the RhoA/ROCK/myosin-dependent cell contractility leading to aggressive cell motility in human breast cancer cells." (PMID 27907906, 2016). "Here, we provide evidence that NRF2 deletion inhibits proliferation and metastasis of breast cancer cells by down-regulating RhoA." (PMID 27713154, 2016). "Except for MCF-7 cells, the expression level of RhoA was notably higher in the rest of the breast cancer cells than in COS-7 cells, with highest expression level in SKBR-3 cells." (PMID 26816343, 2016). "Our findings indicate that NRF2 silencing-mediated reduction of RhoA expression contributes, at least in part, to the poor outcome of breast cancer patients with high NRF2 expression." (PMID 27713154, 2016). "Here the authors show that the sodium channel β4 subunit regulates breast cancer cell migration via inhibition of RhoA activation, independently from its function as an auxiliary protein of the sodium channel." (PMID 27917859, 2016). "Taken together, these results suggest that Sema4D from breast cancers can inhibit mineralization by osteoblasts and induce their production of the osteoclast stimulating factor IL-8 in a RhoA-dependent manner." (PMID 26910109, 2016). "Similar to a pro-oncogene, overexpression of NRF2 in breast cancer activates the RhoA gene and its downstream signal proteins, leading to enhanced cell proliferation and metastasis." (PMID 27713154, 2016). "Recently, MKL and SRF were shown to play a key role in metastasis in melanoma and breast cancer xenograft systems providing a strong link to the transcriptional effects of RhoA or RhoC in these processes." (PMID 27600078, 2016). "It has been reported that miR-31 possessed multiple mechanisms to inhibit breast cancer metastasis by partial coordination to repress the metastasis-promoting genes, such as RhoA, ITGA5 and RDX." (PMID 27174918, 2016). "RhoA, as an important small GTPase, is a key factor of cell proliferation and migration in breast cancer." (PMID 27713154, 2016). "Studies of RhoA overexpression in breast cancer cells reveal reduced levels of cell proliferation and invasiveness when treated with RhoA specific siRNAs." (PMID 27304967, 2016).
breast carcinoma (continued). "Overexpression of RhoA is a common event in breast cancer that promotes tumor cell proliferation and metastasis." (PMID 27713154, 2016). "SEMA3A inhibits cell adhesion and migration through an increase in integrin-α2β1 levels and through the promotion of RhoA translation via a mechanism that involves eIF4E in breast cancer models." (PMID 26755661, 2016). "In breast cancer, RhoA and RhoC are both over-expressed and knockdown of each isoform decreased cell proliferation, migration and invasion in TNBC cell line MDA-MB-231." (PMID 27487152, 2016). "ROCK and RhoA are within a signaling pathway that is often misregulated in breast cancer progression." (PMID 27203208, 2016). "Although no constitutively active mutants of Rho GTPases have been detected in human tumors, a correlation between increased expression of RhoA and poor clinical outcome has been demonstrated in breast cancer by both clinical and experimental data." (PMID 27713154, 2016). "An inhibitor that binds between the DH and PH domains of the LARG GEF was identified by virtual screening, and selectively blocks RhoA signaling and tumorigenic behavior of breast cancer cells." (PMID 27304967, 2016). "Depletion of MLK3 or inhibition of its activity results in elevated RhoA activity, excessive FA and stress fiber formation, and decreased cell migration in highly invasive breast cancer cells." (PMID 27213454, 2016). "In MCF-7 breast cancer cells, induction of E-cadherin by actin depolymerization requires RhoA inactivation while dominant active RhoA induces E-cadherin." (PMID 25756282, 2015). "In vitro studies, LPA2 has been verified to regulate LPA-induced breast cancer cells proliferation and migration through Erk or RhoA pathway." (PMID 25209561, 2015). "Later observations indicated that serum deprivation activates NHE1 in breast cancer cells via a sequential RhoA/p160ROCK/p38MAPK signaling pathway, gated by direct protein kinase A phosphorylation and concurrent inhibition of RhoA." (PMID 25514463, 2015). "We found that NGF treatment induced CD44 binding to TrkA at the plasma membrane and subsequent activation of the p115RhoGEF/RhoA/ROCK1 pathway to stimulate breast cancer cell invasion." (PMID 25840418, 2015). "In HCC, melanoma and breast cancer cells, cytoplasmic expression of p27 was found to promote migration and metastasis by inhibiting RhoA activity." (PMID 26271467, 2015). "Dysregulation of small GTPases such as Ras and Rho family GTPases (RhoA, RhoC, Rac1 and Cdc42) is critical to drive the invasion and metastasis of a variety of cancers, including breast carcinomas." (PMID 24587105, 2014). "Consistent with inhibited biosynthesis of isoprenoids we detected markedly reduced levels of active (i.e. geranylgeranylated) RhoA in KLK5-expressing breast cancer cells." (PMID 24158494, 2014). "Accordingly, Rho proteins, in particular RhoA and RhoC, play critical roles in tumor invasion and metastasis in a variety of cancers including breast cancer." (PMID 24587105, 2014). "Collectively, the data further demonstrated that RhoA and RhoC are targets of PFIs in breast cancer cells." (PMID 24587105, 2014). "Taken together, the data support a mechanism by which AGOH inhibits the invasive potential of breast cancer cells, at least in part, through inhibition of RhoA and RhoC activity." (PMID 24587105, 2014). "Ras homolog gene family member A (RhoA) is involved in Wnt-5a–induced migration of gastric and breast cancer cells." (PMID 24351810, 2013). "Taken together, these data establish that BCAR3 functions as a positive regulator of cytoskeletal remodeling and adhesion turnover in invasive breast cancer cells through its ability to influence the balance between Rac1 and RhoA signaling." (PMID 23762409, 2013).
breast carcinoma (continued). "Our results show that blocking total LMW-PTP and its slow isoform by siRNA in the MDA-MB-435 cell line, a breast cancer invasive cell line, results in increased migratory potential, which our results suggest to occur through RhoA." (PMID 24086724, 2013). "Based on these data, we suggest that BCAR3 controls the balance between Rac1 and RhoA signaling in invasive breast cancer cells and, through this activity, functions as a positive regulator of actin cytoskeletal/adhesion remodeling and cell motility." (PMID 23762409, 2013). "Phosphoinositide 3-kinase/protein kinase B (PI3K/Akt)-dependent phosphorylation of glycogen synthase kinase-3β (GSK3β) and RhoA activation regulate Wnt-5a–induced gastric cancer cell migration, in line with results for breast cancer cells." (PMID 24351810, 2013). "RhoA has been reported to be one of the targets of miR-31 in breast cancer, and plays an important role as a molecular switch in transducing extracellular signals to actin and microtubule cytoskeleton." (PMID 24004633, 2013). "Taken together, we demonstrated for the first time that Wnt5a promotes breast cancer cell migration via Dvl2/Daam1/RhoA." (PMID 22655072, 2012). "In our previous study, we demonstrated that hPTTG1 can regulate the actin cytoskeletal dynamics of breast cancer cells by activating GEF-H1/RhoA signaling to promote breast cancer metastasis." (PMID 22789011, 2012). "In summary, we presented the first direct evidence that Wnt5a promotes breast cancer cell migration via Dvl2/Daam1/RhoA." (PMID 22655072, 2012). "We showed here that Wnt5a activated Dvl2, Daam1 and RhoA, and promoted migration of breast cancer cells, which was, however, abolished by Secreted Frizzled-related protein 2 (sFRP2) pretreatment." (PMID 22655072, 2012). "RhoA protein levels were significantly increased in breast cancer compared with the matched normal tissue." (PMID 22110952, 2011). "Previous studies using HeLa or breast cancer cells showed that active RhoA is required for the induction of membrane ruffles in migrating cells also mediated by Dia1 and not ROCK." (PMID 21943101, 2011). "miR-31 has been shown to be an inhibitor of breast cancer metastasis by targeting RhoA, RDX and ITGA which are involved in tumor motility, invasion and resistance to anoikis." (PMID 21483847, 2011). "Lovastatin-treated breast cancer cells showed changes in the activity of various small GTPases, primarily through the inhibition of the isoprenylation of RhoA." (PMID 20205716, 2010). "A special emphasis has already been placed on the role of Rho GTPases, and especially RhoA, Rac1 and cdc42, as ER-negative modulators in human osteosarcoma and breast cancer cells." (PMID 15642170, 2005). "The reciprocal antagonism between the actions of Rac1 and RhoA on breast cancer cell NHE1 activity, motility and invasive capacity is identical to that reported for movement/migration and actin cytoskeleton remodelling in other cell systems." (PMID 15535843, 2004). "Moreover, ANLN promoted doxorubicin resistance through direct interaction with RhoA in breast cancer cells." (PMID 41513610, 2026). "Notably, the upregulation trend of RHOA lactylation in breast cancer tissues was even more obvious than that of RHOA." (PMID 41291745, 2025). "In addition, we evaluated RHOA expression and lactylation in fresh breast cancer specimens and found that RHOA expression and lactylation were significantly upregulated in most paired breast cancer tissues compared with adjacent normal counterparts." (PMID 41291745, 2025). "The opposing effects of RhoA GTPase as compared to RhoC GTPases may indicate the independence of both GTPases in breast cancer progression, which needs to be investigated in future studies." (PMID 40214422, 2025). "Consistent with this, upregulated expressions of RhoA and RhoC have been reported in breast cancer." (PMID 40214422, 2025).
breast carcinoma (continued). "Additionally, when P18 was applied to MDA-MB-231 and MDA-MB-436 breast cancer cells, a slight upregulation of RhoA and Cdc42 was observed." (PMID 38927935, 2024). "Although the role of this gene in breast cancer is still unclear, there could be an indirect link via the role of RhoA GTPases in breast tumorigenesis." (PMID 37559094, 2023). "We investigated Wnt/PCP-mediated spatiotemporal dynamics of GTPase signaling in real time via time-lapse imaging in collectively migrating breast cancer cells by monitoring GTPase activity using stably expressed Rac1 or RhoA fluorescence resonance energy transfer (FRET) biosensors." (PMID 37147680, 2023). "We further find that Vangl-dependent Wnt/PCP signaling at the leading edge of migrating breast cancer cells results in increased RhoA GTPase activity and formation of pro-migratory protrusions, resulting in collective cell migration in vitro and invasion ex vivo." (PMID 37147680, 2023). "Taken together, we may conclude that FMNL2 suppressed migration and invasion of breast cancer cells by inhibiting RhoA/LIMK/Cofilin pathway through a reduction of cytoplasmic p27." (PMID 35379791, 2022). "Thus, we assume that this miR-125b/STARD13 axis enhances breast cancer stemness probably through RhoA and Hippo signaling, which should be further investigated." (PMID 35057866, 2022). "Finally, we did a preliminary in silico analysis of SNTA1, p66Shc and RhoA proteins in The Cancer Genome Atlas (TCGA) in the breast cancer cohort, in order to confirm the prognostic value of the proteins in this study." (PMID 35273919, 2022). "Based on the cross-talk of integrins and FAK and integrin-mediated regulation of the activity of Rho family proteins in cell migration, the expression of Rho family proteins, including Rac1, RhoA, Cdc42, and integrins, is detected in breast cancer cells after CuB exposure." (PMID 36362132, 2022). "In all, these data suggest that the effects of FMNL2 on breast cancer metastasis may be contributed by the regulation of RhoA/LIMK/Cofilin pathway." (PMID 35379791, 2022). "RhoA dysregulation is observed in breast cancers contributing to progression and metastasis." (PMID 35273919, 2022). "Suppressing DLC1 degradation could inhibit the migration through the DLC1/RhoA pathway in breast cancer." (PMID 35223504, 2022). "For instance, repression of integrin expression by MYC in breast cancer cells has been linked to suppression of cell migration and metastasis, while another report suggests that Skp2 cooperates with MYC to induce RhoA transcription, thereby promoting metastasis." (PMID 36860495, 2022). "However, no constitutively active Rho GTPase mutations have been found in human cancers, and clinical and experimental studies show a link between enhanced RhoA expression and poor clinical outcome in breast cancer." (PMID 35571115, 2022). "As shown in the results above, SNTA1/p66Shc signaling axis contributed to RhoA activation in metastatic breast cancer cells; whereas cytochalasin D mediated actin depolymerization destabilized this transduction axis reducing RhoA activation levels in these cells." (PMID 35273919, 2022). "However, our data indicated that FMNL2 interacted with RhoA, other than Rac1 in breast cancer cells." (PMID 35379791, 2022). "However, recent studies have also suggested a tumor-suppressing role for RhoA in breast cancer and colorectal cancer in certain contexts." (PMID 33546351, 2021). "CXCR4 may also couple to G12/13, promoting metastasis in a RhoA-dependent manner in basal-like breast cancer cells." (PMID 34943797, 2021).
breast carcinoma (continued). "For instance, RhoA/Rho-associated coiled-coil kinase 1 (ROCK1)-activated myosin light-chain (MLC) and FAK signaling were involved upon hypoxia in the matrix contraction, FAs formation and motility of breast cancer cells." (PMID 33562737, 2021). "Moreover, CD151 has been shown to activate RhoA by facilitating integrin α3β1 and Rho controls dimerization of ErbB2, thus promoting motility and metastasis of breast cancer." (PMID 34108040, 2021). "Therefore, we considered the multi-RG combination SF1 + TRA2B + THRAP3 + RHOA + QRICH1 as the most promising choice for breast cancer research (both in breast cancer tissues and cell lines)." (PMID 34895237, 2021). "We showed that RKIP stimulated the GTPase activity of RhoA to inhibit breast cancer cells invasion." (PMID 34465801, 2021). "To investigate whether RhoA and RhoC expression affect the invasive potential of breast cancer cells, we conducted transwell invasion assays." (PMID 34513691, 2021). "Therefore, we recommend that SF1 + TRA2B + THRAP3 and THRAP3 + RHOA + QRICH1 be adopted as the RG combinations for breast cancer tissue and cell line research, respectively." (PMID 34895237, 2021). "Overall, our research indicates that MEX3A and RhoA/ROCK1/LIMK signaling may be new targets for breast cancer treatment." (PMID 34486491, 2021). "Finally, we assessed the MEX3A dependent regulation of RhoA/ROCK1/LIMK1 signaling pathway involved in the progression of breast cancer." (PMID 34486491, 2021). "The increased expression of RhoA or ROCK1 is related to the progression of breast cancer." (PMID 34486491, 2021). "Although our study did not address the causal role of ZEB1/2 in RKIP-mediated regulation of E-cad expression, our results conclusively demonstrated a link between RKIP, Erk, GEF-H1, RhoA, and E-cad expression in triple negative basal epithelial-like breast cancer cell lines." (PMID 34465801, 2021). "Thus, we set out to study how RhoA- and RhoC-GTPase influence the cell-cell junctions in aggressive breast cancers." (PMID 34513691, 2021). "As RhoB is expressed at very lower levels in basal-like breast cancer cell lines, we hypothesized that Rhosin treatment would have the same effect as RhoA siRNA." (PMID 33162807, 2020). "Studies with RhoA have demonstrated controversial effects on breast cancer cell migration." (PMID 32992837, 2020). "In general, however, the role of RhoA in invasion and metastasis in breast cancer is controversial." (PMID 33291460, 2020). "RhoA overexpression in breast cancer is correlated with proliferation, invasion, and angiogenesis." (PMID 32392742, 2020). "We could observe that Triptorelin induces RhoA activity in a time-dependent manner in mesenchymal transformed breast cancer cells." (PMID 33087801, 2020). "As a therapeutic approach inthis field, microRNA targeting against VIM was shownto decrease breast cancer invasion in animal studies.RhoA is another small GTPase with several functions,and it is known to be a key effector in the polymerizationof actin filaments." (PMID 31606974, 2020). "In addition to reducing RSU1, miR-182-5p promotes tumor cell proliferation, invasion and migration by targeting FOXF2, RECK and MTSS1, and the suppression of MTSS1 (MIM) by miR-182 activates RhoA and promotes breast cancer metastasis." (PMID 32751711, 2020). "Furthermore, the interaction between GIPC1 and MyoGEF, which is also a RhoA GEF, has been implicated in the activation of RhoA as well as breast cancer invasion." (PMID 32377503, 2020). "However, recent work in our lab has shown an important role for RhoA activation for inhibiting breast cancer proliferation." (PMID 32992837, 2020). "ATGR1/RhoA/JNK signaling was correlated with PODXL2 expression in breast cancer." (PMID 32669966, 2020). "Similar to RhoA, RhoB effects on breast cancer migration and invasion are complex." (PMID 32992837, 2020).